CLDN2 (claudin 2)
Description:
Forms paracellular channels: polymerizes in tight junction strands with cation- and water-selective channels through the strands, conveying epithelial permeability in a process known as paracellular tight junction permeability. In intestinal epithelium, allows for sodium and water fluxes from the peritoneal side to the lumen of the intestine to regulate nutrient absorption and clear enteric pathogens as part of mucosal immune response (By similarity). In kidney, allows passive sodium and calcium reabsorption across proximal tubules from the lumen back to the bloodstream (By similarity). In the hepatobiliary tract, allows paracellular water and cation fluxes in the hepatic perivenous areas and biliary epithelium to generate bile flow and maintain osmotic gradients (By similarity).
Synonyms: OAZON; claudin-2
Tractability: Antibody: its Gene Ontology location is reachable by antibodies, with high confidence; UniProt places it where antibodies can reach, with medium confidence; UniProt predicts a signal peptide or a membrane-spanning region; the Human Protein Atlas places it where antibodies can reach. PROTAC: UniProt records ubiquitination sites on it.
Gene: Protein-coding gene on chromosome X (106,900,125 to 106,930,862, forward strand). Ensembl gene ENSG00000165376.
Subcellular location: Cell junction, tight junction; Cell membrane
Subcellular location (Human Protein Atlas): Cell Junctions; Plasma membrane; Nucleoli; Nucleoplasm; Vesicles
Pathways (Reactome):
Cell-Cell communication: Tight junction interactions
Gene Ontology:
Molecular function: identical protein binding; paracellular tight junction channel activity; protein binding; structural molecule activity
Biological process: paracellular transport; calcium-independent cell-cell adhesion; cell-cell adhesion; innate immune response in mucosa; regulation of bile acid secretion; regulation of intestinal D-glucose absorption; regulation of intestinal lipid absorption
Cellular component: cell junction; cell-cell junction; plasma membrane; tight junction; bicellular tight junction; membrane
Homologues: Orthologues: chimpanzee CLDN2 (100% identical), macaque CLDN2 (98% identical), pig CLDN2 (96% identical), dog CLDN2 (93% identical), rabbit CLDN2 (92% identical), mouse Cldn2 (91% identical), rat Cldn2 (91% identical), guinea pig CLDN2 (89% identical), tropical clawed frog cldn2 (58% identical), zebrafish cldn2 (48% identical). Paralogues in human: CLDN14 (46% identical), CLDN19 (37% identical), CLDN6 (37% identical), CLDN9 (37% identical), CLDN4 (36% identical), CLDN3 (36% identical), CLDN7 (35% identical), CLDN1 (33% identical), CLDN17 (33% identical), CLDN20 (33% identical), CLDN5 (32% identical), CLDN8 (32% identical), and 10 more.
Diseases named in the same sentence as CLDN2 in open-access papers:
CLDN2 is named in the same sentence as 146 diseases in open-access papers, as found by Europe PMC text mining. Sharing a sentence is not in itself a finding about the gene and the disease. The quoted sentences say what the papers report.
colitis (76 papers, 2011 to 2025). Inflammation of the colon. "Expression of Claudin 1 diminishes upon chronic exposure to LPS challenge, whilst Claudin 2 expression is associated with protection of microbial-induced colitis." (PMID 39125663, 2024). "Claudin-2 promotes colitis-associated mucosal healing, which protects against colitis-associated colon cancer." (PMID 39770982, 2024). "Coimmunofluorescence analysis using anti-CLDN2 and -Survivin antibody showed a positive correlation in colitis-associated regenerative crypts." (PMID 37815870, 2023). "In face of above findings, we further examined transcriptomic changes associated with CLDN2 changes during colitis-associated MH." (PMID 37815870, 2023). "We next tested the significance of the gain or loss of function of the CLDN2/Survivin axis in colitis-associated repair/MH." (PMID 37815870, 2023). "CLDN2 deficiency associates with impaired MH-associated gene transcription in both colitis-challenged mice and patients with IBD." (PMID 37815870, 2023). "Taken together, above data demonstrated dynamic regulation of CLDN2 expression during colitis where CLDN2 upregulation associated with MH." (PMID 37815870, 2023). "This study was undertaken to examine if an interplay between autophagy and claudin-2 protects from colitis and associated epithelial injury." (PMID 37460613, 2023). "A recent report that depleting the T and B lymphocytes in Villin-Cldn2TG mice renders them susceptible to T cell colitis contrasts above findings; however, it also suggests a direct/indirect role of CLDN2 in mucosal immune homeostasis." (PMID 37815870, 2023). "Cldn2 loss also resulted in impaired recovery from colitis and increased injury when mice were subjected to intestinal injury by other methods." (PMID 37815870, 2023). "In contrast, increased Claudin2 is associated with CR infection, and the overexpression of Claudin 2 in intestinal epithelial cells enhanced colitis in mice." (PMID 37111225, 2023). "Loss of Cldn2 expression promotes proinflammatory and proapoptotic responses during recovery from colitis." (PMID 37815870, 2023). "In other words, Polycan has a protective effect on intestinal length shortening with weight loss in DSS-induced colitis mice and intestinal permeability, by regulating adhesion proteins (e.g., ZO-1, occludin, and claudin-2)." (PMID 37834221, 2023). "Having characterized that Cldn2 loss promotes proinflammatory and proapoptotic programs during colitis/recovery, we further examined its relevance to IBD." (PMID 37815870, 2023). "Mouse models with altered expression of specific claudin genes either develop spontaneous mucosal inflammation (CLDN7 knockout) or exhibit enhanced (CLDN1 overexpression, or CLDN2 knockout) or reduced (CLDN2 overexpression) susceptibility to induced colitis." (PMID 35805947, 2022). "Studies have shown that claudin‐2 deficiency slows the progression of colitis and leaky barrier defects, and claudin‐2 is known to lead to the sufficient formation of cation‐selective channels to convert “tight” junctions into leaky channels." (PMID 36458537, 2022). "Herein, we are the first to investigate the effects of miRNA-182-5p and its association with Claudin-2 in dextran sulphate sodium (DSS) induced colitis." (PMID 34623552, 2021). "A transgenic mouse with targeted overexpression of claudin-2 in the colon was protected against colitis-associated injury." (PMID 31726679, 2019). "Based on ex vivo experiments deficiency of matriptase in St14 hypomorphic mice caused enhanced claudin-2 expression and it delayed the recovery of barrier integrity, when intestinal mucosa was injured during dextran sodium sulfate-induced colitis." (PMID 26488575, 2015). "Given that claudin-1 and claudin-2 play distinct roles in epithelial barrier integrity, the differential regulation of these proteins by IL-9 across various colitis models may underlie the context-dependent role of IL-9/Th9 cells in colitis development." (PMID 40771819, 2025).
colitis (continued). "An increased expression of claudin-2 is associated with enhanced permeability, diarrhea, and inflammation; however, animals over-expressing or under-expressing the claudin-2 isoform exhibit different responses to the induction of colitis." (PMID 39334888, 2024). "Overall, these results supported a role for CLDN2 in promoting colitis-associated MH." (PMID 37815870, 2023). "Claudin-2 overexpression protects mice from DSS-colitis and associated epithelial injury." (PMID 37460613, 2023). "Colitis-associated CLDN2 upregulation correlates with crypt regeneration/repair." (PMID 37815870, 2023). "Inhibiting EGFR signaling inhibits recovery from colitis and associated CLDN2 upregulation." (PMID 37815870, 2023). "However, different from the protective role in colitis, claudin-2 is upregulated by Cdx-associated Wnt signaling activation and contributes to tumorigenicity of CAC by promoting cell proliferation via EGFR/ERK signaling in vitro." (PMID 31316506, 2019). "Interestingly, in oxazolone colitis model, there was a downregulation in the expression of claudin 2 in IL-9-deficient mice than wild-type mice." (PMID 29881387, 2018). "We found that DSS-induced colitis was associated with decreased expression of colonic claudin-1, claudin-3, claudon-5, claudin-7 and claudin-8, and also increased expression of colonic claudin-2." (PMID 22073304, 2011). "Finally, the intestinal permeability was investigated, showing an increased permeability for 4 kDa FITC-dextran in colitis mice associated with a decreased mRNA level of junctional proteins Cldn1, Cldn2, Cdh1 and Ocln and an unaltered expression of scaffolding protein Zo1." (PMID 34248633, 2021). "The effect was associated with the increase in expression of claudin-2 expression with IL-9 treatment and reduction in claudin-2 expression with IL-9-deficiency, indicating that IL-9 disrupts intestinal permeability by enhancing the expression of claudin-2, which helps in promotion of colitis." (PMID 31035677, 2019). "Compared to the normal group, the colitis mice exhibited significantly increased mRNA expression levels of epithelial barrier proteins (CLDN-2, occludin, and ZO-1) as well as the mucin barrier protein (MUC2) in their colon tissues." (PMID 40529132, 2025). "Previous studies showed that overexpression or up-regulation of claudin-2 increased intestinal permeability and worsen colitis." (PMID 39841790, 2025). "Claudin-2 (Cldn2), reported to protect mice against induced colitis, was also expressed at significantly higher levels in Bp 531D-gavaged mice compared to controls." (PMID 40631899, 2025). "Tight junctions were a key pathway identified to be regulated in disease remission, with a number of claudins observed to be upregulated, and claudin 2 has established mechanistic links to colitis progression." (PMID 38531874, 2024). "Specifically, DSS-induced colitis markedly decreased the expression of ZO-1, occludin, and claudin-1 and dramatically increased the expression of claudin-2 at the mRNA levels; nevertheless, the abnormal expression was corrected by the UTI treatment." (PMID 38397811, 2024). "We identified significant decreases in claudin 2 levels in the distal and middle colon of mice following development of colitis." (PMID 38531874, 2024). "Our results revealed that zonulin and claudin-2 were present at significantly increased levels in the cecal mucosa in the P. aeruginosa-infected colitis mice via the treatment of LGG or BL compared with the sham group." (PMID 38397855, 2024). "The expression of claudin-2 was significantly increased in the DSS-induced colitis group compared to the non-colitis control group, with extensive expression in both the surface and glandular epithelium." (PMID 39334888, 2024). "This increase in claudin-2 expressionin colitis acts as a protective mechanism against diarrhea by inducingselective cation channels of TJ, increasing the paracellular permeabilityof Na2+ and water." (PMID 39022369, 2024).
colitis (continued). "Claudin-2 protein levels were significantly increased in colitis animals compared to the non-colitis controls regardless of nobiletin treatment, and nobiletin treatment of the colitis group significantly reduced the expression of the claudin-2 isoform." (PMID 39334888, 2024). "At the transcriptional level, the recovery of colitis-injured mucosa in vitro is impeded by upregulated Claudin-2 expression facilitated through a CDX2-dependent mechanism." (PMID 38619276, 2024). "Exosomal CagA promotes colitis by caudal type homeobox 2 (CDX2)-dependent claudin-2 upregulation in the intestinal epithelial cells." (PMID 39610678, 2024). "The levels of claudin-2 mRNA isoforms relative to β-actin decreased significantly compared to the non-colitis controls." (PMID 39334888, 2024). "In this regard, inflammation/injury-associated CLDN2 upregulation was restricted to the SCA-1+, Ki67+, and/or Survivin+ cells, and Cldn2 loss impaired the recovery of mice from colitis." (PMID 37815870, 2023). "In accordance with this, current data suggest a positive association between CLDN2 expression and IEC survival during colitis/recovery." (PMID 37815870, 2023). "To further determine a causal role for CLDN2 in colitis-associated MH, we subjected Cldn2KO mice and littermate WT mice to DSS-induced colitis and recovery." (PMID 37815870, 2023). "Collectively, above findings validated that K63-linked ubiquitination at K218 facilitated selective autophagic targeting of claudin-2 under stress conditions including colitis." (PMID 37460613, 2023). "The colitis group had higher gene expression of claudin-1 and claudin-2 compared to the Sham group (8.12±1.79 vs 0.94±0.16 and 3.51±0.67 vs 1.01±0.13, respectively, P<0.05)." (PMID 37909497, 2023). "The complex role of claudin-2 in maintaining intestinal mucosal homeostasis offers potential opportunities for the treatment of colitis." (PMID 37646028, 2023). "Overall, our data indicated that the EGFR/CLDN2/Survivin axis and DDR signaling play a crucial role in colitis/inflammation-associated MH." (PMID 37815870, 2023). "An upregulated SCA-1 expression characterized the regenerative crypts, which also colocalized with CLDN2 in mice subjected to DSS-induced colitis/recovery and/or chronic colitis." (PMID 37815870, 2023). "Further analysis of the published microarray and RNA-Seq data sets from our and other laboratories from mice subjected to DSS-induced colitis validated Cldn2 downregulation in colitis versus naive WT mice." (PMID 37815870, 2023). "Previous studies show that claudin-2 overexpression or up-regulation of claudin-2 expression increased intestinal permeability, and deteriorated colitis." (PMID 37784173, 2023). "We validated the role of CLDN2 in modulating Survivin expression in multiple murine models of colitis and recovery and ex vivo studies using colonic crypts subjected to injury/repair." (PMID 37815870, 2023). "We carefully examined CLDN2 regulation during colitis, as previous reports have shown variable CLDN2 expression in mouse models of colitis." (PMID 37815870, 2023). "Nevertheless, genetic modeling of pathological claudin-2 expression, as in IBD, protects mice from colitis induced by epithelial injury while claudin-2 KO mice develop severe colitis." (PMID 37460613, 2023). "In this study, we revealed the protective effects of FGR against DSS-induced colitis via the regulation of expression of tight junction proteins, such as ZO-1, occludin, and claudin-2, and improvement of intestinal barrier dysfunction." (PMID 36829894, 2023). "We further found that Cldn2 mRNA expression was downregulated during DSS-induced colitis; however, it was significantly upregulated during recovery along with Pcna and Mki67ip (markers of crypt proliferation)." (PMID 37815870, 2023). "Overall, above findings demonstrated an unexpected dichotomy in the effects of CLDN2 expression upon colitis and CAC." (PMID 37815870, 2023).
colitis (continued). "Our data that DSS-colitis induced sharp decreases in claudin-2 expression contrasts with some published studies that have shown an increase in claudin-2 expression in mice subjected to DSS-colitis." (PMID 37460613, 2023). "Under stress including colitis, claudin-2 protein is degraded by P62/SQSTM1-assisted autophagy to promote survival of intestinal epithelial cells." (PMID 37460613, 2023). "Our findings also help explain previous findings that mice overexpressing claudin-2 in their intestinal epithelium are protected from DSS-colitis while claudin-2 KO mice develop severe colitis." (PMID 37460613, 2023). "Studies have demonstrated that claudin-2 not only inhibits colitis-induced cell death but also suppresses colitis-induced immune activation and signal transduction." (PMID 37646028, 2023). "We found a similar decrease in claudin-2 expression using lysates prepared from the distal colon from mice subjected to DSS-colitis (2.5% w/v) for 7 days." (PMID 37460613, 2023). "Of note is that increased claudin-2 expression by intestinal epithelial cells is correlated with colitis and inflammatory bowel disease." (PMID 36839844, 2023). "Hence, we examined whether CLDN2 regulates Survivin expression to regulate colitis-associated MH." (PMID 37815870, 2023). "For example, colitis resistance was shown in mice transgenically modified to produce high levels of claudin 2, presenting the possibility that the increased claudin 2 levels found in human disease are beneficial." (PMID 37239907, 2023). "mRNA expression of Cldn1 and Cldn2 was significantly altered in control Muc13−/− mice compared to wildtypes and during the course of colitis." (PMID 37174625, 2023). "The contrasting increase in colitis in Cldn2KO mice suggested a rather adaptive role of colitis-induced CLDN2 upregulation." (PMID 37815870, 2023). "Specifically, CagA upregulated Claudin-2 expression at the transcriptional level via a CDX2-dependent mechanism to slow the restoration of wounded mucosa in colitis in vitro." (PMID 35331316, 2022). "Meanwhile, it has been suggested that IL-22 exhibited protective ability in regulation of gut inflammation by stimulating colon epithelial cell lines to produce IL-10 and SOCS3 to ameliorate DSS-induced colitis via upregulating claudin-2 expression." (PMID 36092152, 2022). "According to our in vitro experimental results, CLDN2 expression in colon tissue was strongly reduced in the mice treated with the miR-195-5p mimic compared with the vehicle after the induction of colitis (p < 0.05)." (PMID 35628650, 2022). "We demonstrated that exosomal CagA from H. pylori disrupts the barrier function of intestinal epithelial cells in colitis by facilitating Claudin-2 expression." (PMID 35331316, 2022). "The Cldn2 gene is highly expressed in the gut tissue of colitis patients, whereas ZO1is downregulated." (PMID 35263357, 2022). "Claudin-2 is unregulated in inflammatory bowel disease (IBD), and its deficiency reduces colitis progression and barrier defect, suggesting that its reduced expression prevents the inflammation of the intestinal barrier." (PMID 36793340, 2022). "The previous reports found that the Cldn2 gene is highly expressed in the gut tissue of colitis patients, whereas ZO1is downregulated." (PMID 35263357, 2022). "Strikingly, overexpression of claudin 2 in transgenic mice and in a colonic epithelial cell line showed that claudin 2 offers protection against DSS-induced colitis and also altered the proportion of FOXP3+ regulatory T cells in injured colonic tissue." (PMID 33673239, 2021). "Collectively, all the effects of miRNA-182-5p inhibitor in colitis can be achieved via claudin-2 overexpression." (PMID 34623552, 2021). "Consistent with the role of miRNA-182-5p, claudin-2 overexpression also exerted protective effects on DSS-induced colitis in mice." (PMID 34623552, 2021). "Inhibition of miRNA-182-5p exerted protective effects on colitis via targeting and upregulating claudin-2." (PMID 34623552, 2021).